ANXA2 (annexin A2)
Diseases named in the same sentence as ANXA2 in open-access papers (continued):
Sharing a sentence is not in itself a finding about the gene and the disease.
cancer (continued). "A further study used annexin A2 (AnxA2) antibody-conjugated curcumin-loaded PLGA NPs against cancer cells expressing AnxA2 surface antigen." (PMID 38399327, 2024). "Further research is required to identify the molecular mechanisms underlying the interaction between ANXA2 and TTK in other cancers." (PMID 38658569, 2024). "Given its multifaceted roles in cancer progression, ANXA2 has emerged as a promising target for therapeutic intervention." (PMID 39594718, 2024). "In the LUAD, LINC01614 formed a trimeric complex with ANXA2 and p65 to facilitate the latter two molecules’ interaction and the activation of NF-κB, eventually elevating cancer cell growth." (PMID 38688909, 2024). "Annexin A2 (AnxA2)-a member of the calcium dependent phospholipid binding proteins was proposed as a downstream molecule of the CCL18-PITPNM3 signaling in cancer cells." (PMID 39044824, 2024). "Wound healing and transwell assays showed that the migration and invasion abilities of ANXA2 overexpression cancer cells were enhanced." (PMID 38658569, 2024). "In our study, we identified a new role of the LOXL4 secreted in TNBC progression: in addition to its traditional collagen cross-linking function, it also targets cancer cell surface annexin A2 as a substrate for enzymatic cross-linking modification." (PMID 38595825, 2024). "This inhibition mechanism was previously attributed to other natural compounds, like ginseng (G-Rg5 and G-Rk1), which can bind to Annexin A2 resulting in increased apoptosis in cancer cells." (PMID 38414081, 2024). "To study the clinical effects of ANXA2 in ESCC, we use shRNAs to establish stable ANXA2-knockdown cancer cells transfected with a luciferase reporter gene plasmid." (PMID 38658569, 2024). "Anxa2 is has an interesting connection to the problem of cell softening, because it is overexpressed in many types of cancer." (PMID 39139811, 2024). "Furthermore, clinical studies have demonstrated that ANXA2 protein expression is associated with aggressive cancers, drug resistance, and radiotherapy resistance, suggesting that ANXA2 may be an oncogene that contributes to the malignant behavior of cancer cells." (PMID 38658569, 2024). "The expression of activated annexin A2 (pANXA2), a target of this agent, is low in metabolically less active cancer cells." (PMID 38558990, 2024). "In vitro experiments by knockdown and overexpression of ANXA2 revealed that ANXA2 promotes the progression of ESCC by enhancing cancer cell proliferation, migration, and invasion." (PMID 38658569, 2024). "Despite its significant role in cancer progression, the high immunohistochemical expression of ANXA2 in normal cervix remains poorly understood." (PMID 37185759, 2023). "Following our discovery of the role collagen-I plays in the post-translational phosphorylation and localization of Annexin A2, our next step was to investigate the functional consequences of this relationship in cancer cells." (PMID 37941562, 2023). "Annexin A2 (ANXA2) is a cancer biomarker and is involved in the occurrence and development of a variety of tumors, particularly PAAD." (PMID 36453020, 2023). "We then demonstrated that reducing Annexin A2 expression decreases the degradation of fibronectin by cancer cells and this effect on fibronectin turnover is increased according to collagen-I abundance." (PMID 37941562, 2023). "ANXA2 also attracted great attention from investigators to be an emerging biomarker and potential therapeutic target for aggressive cancers." (PMID 36786600, 2023). "ANXA2 was upregulated in most types of cancer, which allowed it to function more fully as an potential oncogene." (PMID 36713082, 2023). "The ANXA2 expression negatively correlated with TMB in five types of cancer (all r < 0): CESC (p = .022), LAML (p = .0087), LUAD (p = .0014), LUSC (p = .0013), and PRAD (p < .001)." (PMID 36713082, 2023). "Taken together, this previously un-annotated cancer-specific enhancer represents a novel regulator of ANXA2 in MBC." (PMID 37685859, 2023).
cancer (continued). "AnxA2 is a multifunctional protein, which is frequently deregulated–in most cases undergoing upregulation–in many types of cancers including those of the nervous system." (PMID 37250892, 2023). "One such mediator for this TME-cancer cell cross-talk is Annexin A2 due to its transient intra- to extra-cellular cycling and its role in ECM degradation." (PMID 37941562, 2023). "The expression of ANXA2 positively correlated with MSI in seven types of cancer (all r > 0): COAD (p < .001), KIRC (p = .032), READ (p = .018), SARC (p < .001), STAD (p < .001), TGCT (p = .0095) and UCEC (p < .001)." (PMID 36713082, 2023). "Ultimately, we have shown that the phosphorylation, location and functionality of Annexin A2 in cancer is regulated by the TME." (PMID 37941562, 2023). "When 24 types of immune cells were investigated, ANXA2 expression variably correlated with them in 32 types of cancer (except CHOL)." (PMID 36713082, 2023). "ANXA2 is a member of the annexin family of proteins that is expressed on the surface of various cancer cells and mediates intercellular and intracellular communication and cell survival." (PMID 36916296, 2023). "The overexpression of AnxA2 in cancers often correlates with resistance to treatment, metastasis, and thus poor prognosis." (PMID 37250892, 2023). "Despite these molecular insights and a number of links between Annexin A2 phosphorylation and cancer, there is scant information regarding the physiological regulation and implications of this in the context of the TME." (PMID 37941562, 2023). "ANXA2 expression was variably related to the immune checkpoints in all 33 types of cancer, with the most relevant correlation being with CD276 (31/33)." (PMID 36713082, 2023). "In line with that finding, the binding of annexin A2 to actin filaments at the C-terminal site contributes to cancer cells’ spread via the regulation of the dynamic remodeling of the actin cytoskeleton." (PMID 37091157, 2023). "In this study, we found that ANXA2 variably correlated with 47 immune checkpoints in 33 types of cancer." (PMID 36713082, 2023). "AnxA2 peptides presented by MHC class II-positive cancer cells can also activate antigen-specific T cells and thus produce an immune response that is potentially useful in immunotherapy." (PMID 37250892, 2023). "Molecular docking confirmed the interaction of major fatty acids with Annexin A2, suggesting a role of açaí seed oil in modulating Annexin A2 expression in these cancer cell lines." (PMID 37512496, 2023). "We observed that an abundance of LOXL4 induces the multimerized form of annexin A2 via cross-linking, resulting in an inhibition of integrin β-1 internalization, which promotes an integrin β-1-mediated elevation of cancer cell outgrowth." (PMID 37091157, 2023). "The ANXA2 expression negatively correlated with MSI in three types of cancer (all r < 0): GBM (p = .027), LUAD (p = .0012) and PRAD (p = .022)." (PMID 36713082, 2023). "This post-translational modification at Tyr24 is of particular interest in malignancy due to the early discovery of phosphorylated Annexin A2 in transformed cells and more recent observations of increased Tyr24 phosphorylation levels in cancer." (PMID 37941562, 2023). "We demonstrated a differential protein expression of ANXA2 in five types of cancer, including COAD, GBM, LIHC, PRAD and STAD." (PMID 36713082, 2023). "ANXA2 is involved in various pathophysiological processes, including epithelial-mesenchymal transition, fibrinolysis and cancer drug resistance." (PMID 36713082, 2023). "The ANXA2 expression positively correlated with TMB in eight types of cancer (all r > 0): COAD (p < .001), LGG (p < .001), PAAD (p < .001), SARC (p < .001), SKCM (p = .002), STAD (p < .001), THYM (p = .0017) and UCEC (p < .001)." (PMID 36713082, 2023).
cancer (continued). "The expression, localization and interactions of Annexin A2 allow it to function as a bi-directional negotiator between the extracellular environment, the cancer cell and back out to the TME." (PMID 37941562, 2023). "We conducted a gene co-expression analysis in 33 types of cancer exploring the correlation between ANXA2 expression and immunomodulators such as immune-activating genes, immune-suppressing genes, chemokine ligands, chemokine receptors and MHC genes." (PMID 36713082, 2023). "Annexin A2 is also located on the cell surface when phosphorylated at tyrosine 23 by the proto-oncogene tyrosine-protein kinase Src in cancer cells." (PMID 37091157, 2023). "On the other hand, AnxA2 peptides presented by MHC class II-positive cancer cells activate antigen-specific T cells and consequently produce an immune response that can be exploited in immunotherapy." (PMID 37250892, 2023). "Exploring the relationship between ANXA2 and DNA methylation will contribute to elucidating the role of ANXA2 in cancer development." (PMID 36713082, 2023). "This includes functionally relevant proteins associated with LN metastasis in cancer such as KRT7, KRT19, SRI, NPM1, Annexin A2 (ANXA2), Annexin A5 (ANXA5)." (PMID 37142981, 2023). "Cells with downregulated ANXA2 (shANXA2 #1/MDA-MB-231) caused Golgi apparatus fragmentation, which is related to reduced secretion of cancer-promoting growth factors." (PMID 36803413, 2023). "Annexin A2 has been known to arrange different molecular mechanisms in cancer progression, as its expression fluctuates in different oncological indications." (PMID 38146364, 2023). "We revealed the relationship between the expression of ANXA2 and the prognosis, immune infiltration and genetic alterations of 33 types of cancer." (PMID 36713082, 2023). "Combining together the TCGA and GTEx databases, 23 types of cancer showed high ANXA2 expression, while five showed low expression." (PMID 36713082, 2023). "In this study, we evaluated the ANXA2 expression in 33 types of cancer and corresponding normal tissues from TCGA." (PMID 36713082, 2023). "Gene Set Enrichment Analysis revealed that Annexin A2 was significantly correlated with immune-related pathways in fifteen cancers." (PMID 36713082, 2023). "Similar to the findings in the mouse models, ANXA2 was highly expressed in the cancer cell compartment, while macrophage staining for ANXA2 was negligible." (PMID 36377658, 2022). "Other circRNA profiling and bioinformatics studies have also identified hsa_circ_0004277 as a promising AML‐related biomarker, and the annexin A2 circRNA has also been highlighted as a promising biomarker and therapeutic in this cancer." (PMID 35297094, 2022). "In the context of cancer, aberrant expression of ANXA2 has been reported in multiple malignancies and demonstrated to predict poor patient outcomes specifically in NSCLC." (PMID 36377658, 2022). "Taken together, these data demonstrate that aberrant ANXA2 expression is an important prognostic factor in multiple cancers, and correlates with malignancy progression." (PMID 35371986, 2022). "ANXA2 overexpression has been connected with various cancer growths, invasion, metastasis, and drug resistance." (PMID 35874629, 2022). "Annexin A2 (ANXA2), also called p36 or annexin II, is a 36 kDa calcium-dependent phospholipid binding protein that is upregulated in multiple cancer types, including pancreatic cancer." (PMID 35204653, 2022). "It has been reported that Anxa2 (Annexin A2) is a profibrotic gene expressed during tissue fibrosis and cancer 21, 38-40." (PMID 34975317, 2022). "Annexin A2 has also been shown to regulate protein oxidation in a study on ANXA2-depleted cancer cells, ANXA2-null mice, and ex vivo human cancer models." (PMID 35158999, 2022). "Annexin A2 (AnxA2), a Ca++-dependent phospholipid-binding protein, is overexpressed in various cancers and facilitates cell migration and invasion." (PMID 36428758, 2022).
cancer (continued). "A recent meta-analysis to evaluate the prognostic value of ANXA2 overexpression in malignant tumors revealed that ANXA2 overexpression correlated with poor outcomes in patients with malignant tumors." (PMID 35371986, 2022). "This study unraveled a possible role for P-gp in signal transduction possibly by interaction with a Src kinase leading to the augmentation of Anxa2 phosphorylation and increased invasiveness in cancer cells." (PMID 36325145, 2022). "The cancer cell adherence of ANXA2 indicating CTC to the endothelium and localization for the development of micro-metastasis were then simulated in vitro and in vivo." (PMID 35685426, 2022). "In this regard, our previous research established the ANXA2-EGFR autocrine loop by demonstrating that ANXA2 in the cancer cell membrane plays a vital regulatory role in EGFR downstream signaling." (PMID 36224238, 2022). "ANXA2 is mainly distributed in the nucleus and cytoplasm, and important role in cancer progression and invasion has been reported." (PMID 35205125, 2022). "Results taken together suggest that cancer cell proliferation, colony formation and migratory potential is inhibited by miR-936 predominantly through downregulation of ANXA2-EGFR signaling and inactivation of terminal functional proteins." (PMID 36224238, 2022). "It is known that ANXA2 has diverse functions, and it is involved in cancer cell motility, invasion, and metastases." (PMID 34240826, 2022). "ANXA2 at the cancer cell membrane surface interacts with EGFR and it is critical for the regulation of downstream signalling." (PMID 36224238, 2022). "In summary, various ANXA2-targeted therapeutic strategies have already been developed and tested, demonstrating antitumor efficacy in some preclinical cancer models." (PMID 36247003, 2022). "This protein is negatively correlated with the differentiation status of ESCC tumors with less differentiated malignant tumors, having the lowest ANXA2 levels." (PMID 35631574, 2022). "The aberrant expression character of ANXA2 showed in a wide range of cancer cells turn it into emerging biomarker for cancers." (PMID 33995636, 2021). "Previous studies indicated that Annexin A2 (ANXA2) was an effective prognostic marker in several cancers, including HCC." (PMID 34575275, 2021). "It is known that ANXA2 overexpress in the surface of cancer cells and have been announced a biomarker of diagnosis and prognosis of cancers." (PMID 33995636, 2021). "In our previous work, we have already identified Anxa2 as a cellular target of (20S) ginsenoside Rh2((20S)G-Rh2), a natural ginseng extract with anti-cancer activity, and (20S)G-Rh2 inhibited NF-κB activation by interfering Anxa2-NF-κB p50 subunit interaction." (PMID 34502195, 2021). "Study showed that cancer cells transfected with an antisense ANXA2 vector show poor capability of division and proliferation." (PMID 33995636, 2021). "In this review article, we discuss the diagnosis and prognosis latent capacity of ANXA2 in progressive cancers, focus on the exploration of restorative interventions targeting ANXA2 in cancer treatment." (PMID 33995636, 2021). "Previous studies demonstrated that ANXA2 plays a crucial role in the development of many cancer types including PDAC." (PMID 34638560, 2021). "(20S)G-Rh2 is a well-described natural chemical from ginseng for its anti-cancer activity, and part of targets and mechanisms has lately been revealed as (20S)G-Rh2 inhibited NF-κB by interacting with Anxa2." (PMID 34502195, 2021). "Investigators used various technologies to target ANXA2 in a preclinical model of human cancers and demonstrated encouraging results." (PMID 33995636, 2021).
cancer (continued). "It would also go beyond the scope of this review to discuss in detail cancer-related animal studies that identified upstream regulators of AnxA2 expression or activity." (PMID 33810523, 2021). "Kim VM and his colleagues developed a Listeria-based, ANXA2-targeting cancer immunotherapy (Lm-ANXA2) and testing its efficacy for PDAC within two murine models." (PMID 33995636, 2021). "As Anxa2 expression and phosphor-Tyr23 are largely evaluated in various cancer types, this regulatory mechanism towards STAT3 somehow outstands as an assignable target for STAT3 inhibition." (PMID 34502195, 2021). "A substantial number of studies in recent years examined AnxA2 in cancer growth and progression in vivo, identifying diverse AnxA2 functions in tumourigenic settings." (PMID 33810523, 2021). "First, ANXA2 expression in OSCC tissues and adjacent non-cancer tissues of 124 patients were detected, and the correlation between ANXA2 expression and clinical parameters were analyzed." (PMID 33658625, 2021). "Recent researches on cancers indicate that Anxa2 is over-expressed in various types of cancers, promotes cancer development, metastasis and chemo-resistance, highly associated with poor prognosis." (PMID 34502195, 2021). "Annexin A2 (ANXA2), expressed on the surface of mononuclear cells, macrophages, endothelial cells (ECs), and various kinds of cancer cells, is a Ca2+-dependent phospholipid-binding protein." (PMID 34599143, 2021). "Although our findings show that annexin A2 was elevated in advanced stage OC, we found that the combination of plasma annexin A2 and CA125 has a better diagnostic performance for early-stage OC in comparison to advanced cancer." (PMID 33406648, 2021). "Anxa2, a Ca2+-dependent phospholipid-binding protein, has been identified as a strong oncogenic driver in human cancers." (PMID 33817317, 2021). "To further confirm expression of Annexin A2 gene in cancers, we performed bioinformatics analysis to detect Annexin A2 gene level in different cancer cells." (PMID 33995636, 2021). "Several studies demonstrated that Tyr23 phosphorylation of ANXA2 enhances cancer proliferation and metastasis." (PMID 34047479, 2021). "A related family member protein anxA2 has a high degree of sequence homology to anxA1 (55%), is upregulated in cancer, and is known to be expressed on endothelium; therefore binding to anxA2 was assessed to ensure antibody specificity." (PMID 32497150, 2020). "The regulation of Annexin A2 (ANXA2) is one of the potential targets for cancer management and treatment." (PMID 33575208, 2020). "The Annexin A2-chickpea lectin interaction at the membrane lattice is essential for ligand-induced MAPK pathway-mediated induction of cancer cell apoptosis." (PMID 32268913, 2020). "Despite the broadly described role of Annexin A2 as a poor-prognosis marker during cancer progression, it has recently been reported to be induced for degradation by other oncogenic E3 ubiquitin-ligases, such as TRIM65." (PMID 31952268, 2020). "In cancers, ANXA2 plays a role in disease progression and down regulation of mRNA expression correlates with resistance to treatment, binding to the bone marrow, histological grade and type, TNM-stage and shortened overall survival." (PMID 33575208, 2020). "Further validation is needed to build upon this study and truly assess the viability of targeting Annexin A2 to prevent cancer metastasis in vivo." (PMID 32629869, 2020). "Knockdown of Annexin A2 attenuated many of the traditional hallmarks of cancer exhibited by MDA-MB-231 cells." (PMID 32629869, 2020). "At present, no study of ANXA2 in myoblasts has been reported, but many studies have shown that ANXA2 is closely related to the proliferation and migration of various cancer cells." (PMID 32328350, 2020). "Following evidence of Annexin A2′s involvement in the migration and invasion in our ER negative cell model, we next investigated its influence on the cancer phenotype with a series of functional assays." (PMID 32629869, 2020).